INS (insulin)
Diseases named in the same sentence as INS in open-access papers (continued):
Sharing a sentence is not in itself a finding about the gene and the disease.
Hyperglycemia (continued). "This reduction is associated with impaired insulin production and hyperglycemia, suggesting that β-cell death does not contribute to GDM during the 2nd and 3rd trimester of pregnancy." (PMID 27563355, 2016). "26RFa reduces glucose-induced hyperglycemia, increases insulin sensitivity and insulinemia." (PMID 27965532, 2016). "It is characterized by hyperglycemia, which can either be due to improper functioning of the pancreatic β-cells which decreases insulin production, or the resistance of body cells to insulin wherein insulin production by β-cells is normal but cells cannot respond to it." (PMID 27625707, 2016). "If glucose metabolism in α- and β-cells controls glucagon and insulin release in hypo- and hyperglycaemia, respectively, it might be reflected by a relatively left-shifted dependence of metabolism on the glucose concentration in the α-cell." (PMID 27044660, 2016). "Especially, when exogenous insulin is administered or circulatory hyperglycemia is combined, the efficiency of 2DG may be further improved since insulin can promote cellular uptake of hexose." (PMID 26939025, 2016). "This surprising finding suggests that a subset of amylin-expressing β-cells may persist following the development of hyperglycemia, which may otherwise remain undetected by insulin staining." (PMID 27111653, 2016). "When clues are provided as an indication of hyperglycemia, patients may need an additional injection of rapid-acting insulin or need to eat less than usual." (PMID 27478509, 2016). "Additionally, F1 and F2 offspring that were exposed to intrauterine hyperglycemia had impaired insulin secretion from the islets." (PMID 26881249, 2016). "They found in both animal models that AMO-mediated suppression of miR-103 and miR-107, which are elevated in the livers of rodents and humans with insulin resistance, significantly alleviate hyperglycemia in large part by promoting insulin signaling in the liver and adipose." (PMID 27112956, 2016). "BSEPS protects against increases in glucose and decreases in insulin that might be attributed to its ability to reduce hyperglycemia." (PMID 27037095, 2016). "However, our study examined the effect of three different concentration of xylose (2.5, 3.33, and 5 g) on postprandial serum glucose and insulin concentrations in subjects with normal glucose levels and hyperglycemia." (PMID 26979433, 2016). "Combined with above evidence, we speculate that the increased plasma HMGB-1 concentrations may largely be due to the presence of insulin resistance and the low chronic inflammation in the context of hyperglycemia." (PMID 27738641, 2016). "The dose of insulin needed to control hyperglycemia is typically high." (PMID 27142369, 2016). "The most frequent anti-diabetic drugs are focused in preventing and reducing hyperglycaemia, and include drugs able to inhibit carbohydrate absorption, endogenous glucose production, insulin sensitizers, insulin secretagogues, insulin receptor agonists, and inhibitors of glucagon release." (PMID 28042834, 2016). "It is important to mention that “rebound hyperglycemia” was also seen when type 2 diabetics were modeled with a validated numerical model that simulated diabetics receiving continuous nutrition while being treated with SQ Lispro insulin for their hyperglycemia." (PMID 26819233, 2016). "Their interference with insulin signaling leads to hyperglycemia and proinflammatory changes." (PMID 27525022, 2016). "Another mechanism may involve an inflammatory effect in the liver that impairs insulin signaling, leading to a failure to suppress glucose production, and ultimately hyperglycemia." (PMID 27560931, 2016). "The later may be transformed into lipid through lipogenesis “de novo” pathway and in turn induce lipotoxicity and glucotoxicity; preventing insulin action or secretion at cellular levels resulting in a hyperglycemia." (PMID 26841874, 2016).
Hyperglycemia (continued). "In patients with heterozygous mutations in the glucokinase gene, the ability to release insulin is not completely lost, and the patient can still respond appropriately to hyperglycemia, albeit at a higher threshold glucose level." (PMID 28702252, 2016). "Combined afferent and efferent VNS caused severe and sustained hyperglycemia without stimulating insulin secretion." (PMID 26884478, 2016). "Another issue that might be of concern is the potential protection of insulin in hyperglycemia induced aggravation of HIRI." (PMID 27656261, 2016). "Given how SST plays a major role in the homeostasis of glucose metabolism, inhibiting the release of insulin, glucagon, and incretins, along with the fact that hyperglycemia is a known side effect of the administration of somatostatin analogues, this was somewhat surprising." (PMID 27399347, 2016). "It seems preferable to search for new agents that will improve insulin sensitivity in the pathway, leading to suppression of hepatic gluconeogenesis, as well as agents able to enhance glucose uptake in order to decrease the hyperglycaemia." (PMID 27562101, 2016). "The phase of relative hyperglycemia observed in this case report was interpreted by the owner as representing a significant counter-regulatory response, even in the absence of documented hypoglycemia, and responded by reducing the insulin dose." (PMID 27766967, 2016). "Future work will be to investigate the changes in plasma insulin concentrations following treatment with the ethyl acetate fraction of crude F. lutea acetone polyphenol extracts to determine the mechanisms of ameliorating hyperglycaemia." (PMID 27029351, 2016). "We hypothesize that metformin use in pregnancy, as an adjunct to insulin, will decrease adverse outcomes by reducing maternal hyperglycemia, maternal insulin doses, maternal weight gain and gestational hypertension/pre-eclampsia." (PMID 27435163, 2016). "EPA corrected postprandial hypertriglyceridemia, hyperglycemia and insulin secretion ability." (PMID 27565734, 2016). "Under reversed day-night regime in the absence of circadian influence, daily exposure to the dietary carbohydrate load contributed another 8% to the evening postprandial hyperglycemia, this time attributable to a decrease in both β cell secretory function and to peripheral insulin resistance." (PMID 27798656, 2016). "Hyperglycaemia and hyperlipidaemia together contribute to a decline in insulin-producing β-cell mass through activation of the transcription factors nuclear factor kappa-light-chain-enhancer of activated B cells (NF-κB) and signal transducer and activator of transcription (STAT)-1." (PMID 27512950, 2016). "Glucocorticoid administration is a well-documented risk factor for feline diabetes and may well have contributed to the onset of hyperglycemia by decreasing insulin sensitivity in this case." (PMID 27766967, 2016). "βGck+/− mice manifested post-prandial hyperglycemia caused by impaired glucose-induced insulin secretion and failed to proliferate β cells in response to insulin resistance by high-fat diet loading." (PMID 26937254, 2016). "Investigations revealed severe hyperglycemia which was poorly responsive to high doses of insulin." (PMID 27891155, 2016). "In addition, short-term treatment of Ks Leprdb/db mice with two structurally distinct proteasome inhibitors, epoxomicin and celastrol, significantly reduced hyperglycemia by concomitantly increasing insulin sensitivity and increasing insulin production." (PMID 27110686, 2016). "Increased free radical formation and compromised antioxidant defense systems have been implicated in the development of diabetic neuropathy, but more complex pathophysiological pathways, such as hyperglycemia, hyperlipidemia and impaired insulin signaling, are also likely to be involved." (PMID 27483315, 2016).
Hyperglycemia (continued). "The pathophysiological presentations of prolonged hyperglycemia may be operationally characterized within insulin-dependent and insulin-independent, type 1 and type 2, diabetic phenotypes, respectively." (PMID 27084094, 2016). "Also, nerve damage, observed in an animal model of T1D, was causally linked to an increased, Ca2+-independent release of the excitatory amino acid glutamate during acute insulin-induced hypoglycaemia or during chronic hyperglycaemia." (PMID 27240327, 2016). "Generally it may be that the body's fuel storage cells (primarily adipose and liver cells) adapt to hyperglycemia through decreasing levels of insulin sensitivity." (PMID 27547764, 2016). "The use of these newer insulin analog preparations during fasting may be more useful, as regular human insulin has a long-lasting peak with a high possibility of late postprandial hyperglycemia." (PMID 27148163, 2016). "Absorption kinetics may be altered when very large doses are delivered to one site, leading to a failure to reduce postprandial hyperglycemia, but with later hypoglycaemia once the insulin is absorbed." (PMID 27435163, 2016). "The hyperglycemia caused by the HFD signals the pancreas to secrete more and more insulin." (PMID 27547764, 2016). "Altogether, these findings suggest that noradrenergic antidepressants might cause hyperglycemia, while some serotonergic agents might enhance insulin sensitivity and reduce hyperglycemia." (PMID 27788267, 2016). "In vitro, ST-EtOAc improved glucose tolerance, reduced hyperglycemia and reduced insulin levels." (PMID 27656144, 2016). "Hyperglycemia exacerbates beta cell dysfunction and depletes insulin secretory reserve." (PMID 27504458, 2016). "Thus, acute septic shock causes hypoglycemia via induction of glucagon resistance, while chronic low-grade inflammation leads to hyperglycemia via induction of insulin resistance." (PMID 27990298, 2016). "For these reasons, we do not think that hyperglycemia or insulin exposure alone is associated with the same lasting effects." (PMID 27518105, 2016). "Reducing glucose and insulin is very important in reducing postprandial hyperglycemia." (PMID 27803937, 2016). "Paradoxically, the protective down regulation of glucose uptake by insulin responsive tissues may leave vascular endothelial cells (VEC) as important targets of hyperglycaemia mediated oxidative insults." (PMID 26790104, 2016). "Importantly, the Pdx1+/−/APP/PS1 mice exhibited worse hyperglycemia with age, and their serum insulin levels were significantly lower than those of the original APP/PS1 mice (p < 0.05 or p < 0.01)." (PMID 27406855, 2016). "This study demonstrated that a multiple low-dose STZ model with moderate hyperglycemia, maintained using insulin therapy, produced deficits in cardiovascular autonomic function without inducing the resting bradycardia or hypotension typical of other STZ models." (PMID 26885531, 2016). "It has been suggested that the hyperglycemia may be due to the different inhibitory effects of pasireotide on pancreatic α- and β-cells, which produce glucagon and insulin, respectively (52, –, 54)." (PMID 26990064, 2016). "Insulin generally attenuates hyperglycemia by lowering postprandial hyperglycemia." (PMID 27977690, 2016). "While we and others only found limited systemic effects, some previous studies reported that melatonin could reduce fasting hyperglycemia and improve insulin desensitization." (PMID 27143993, 2016). "The hyperglycemia improved significantly after starting metformin and basal insulin." (PMID 26788529, 2015). "In contrast, the C57BLKS mice carrying the ob/ob mutation do not adapt to increased insulin requirements and die of severe hyperglycemia." (PMID 26348837, 2015). "The main objective of GC is to reduce hyperglycaemia while determining insulin sensitivity." (PMID 25750607, 2015).
Hyperglycemia (continued). "In this study, we provide evidence that miR-15b and miR-16 may function in insulin signal transduction to protect REC during hyperglycemia, through increased IRTyr1150/1151 phosphorylation." (PMID 25888955, 2015). "Insulin treatment aimed at normalizing glycemia as compared with tolerating hyperglycemia up to the renal threshold significantly reduced the incidence of electrophysiological signs of CIP/CIM and the need for prolonged mechanical ventilation in long-stay medical and surgical ICU patients." (PMID 26242743, 2015). "Reported data showed that MSC could differentiate into insulin-producing cells in vitro, indicating that transplantation of these islet-like cells is able to ameliorate hyperglycemia in diabetic rats." (PMID 26265166, 2015). "If these fail to control hyperglycemia, then insulin is given." (PMID 25982967, 2015). "Upon inadequate insulin secretion, glucose level in the blood increases (hyperglycemia)." (PMID 26561797, 2015). "Ongoing evidence reveals that brain and possibly peripheral insulin resistance and concomitant hyperglycemia may be key metabolic dysfunctions contributing to Alzheimer’s disease." (PMID 25755673, 2015). "One of these patients needed insulin due to hyperglycemia in the post-operative period." (PMID 26268944, 2015). "Moreover, this postmyriocin plasma hyperglycemia and insulin level normalizations are also consistent with the other literature data." (PMID 26380311, 2015). "High doses of glucose infusion may result in hyperglycemia, hypertriglyceridemia, and hepatic steatosis, although these metabolic abnormalities can be prevented to a large extent by insulin treatment targeting normoglycemia." (PMID 25886997, 2015). "Secondly, excess body iron may be directly involved in insulin signaling and is able to form highly reactive free radicals, which can lead to disturbed glucose metabolism and subsequent hyperglycemia." (PMID 26357514, 2015). "However, β-cells often encounter situations of ER overload, for instance, when rapid production of high amounts of insulin is needed in response to hyperglycaemia." (PMID 26257839, 2015). "The aim of the present study was to investigate whether DNJ decreased hyperglycemia by improving insulin sensitivity." (PMID 26690098, 2015). "Therefore, Rg3 has direct glucose lowering effect on hyperglycemia through enhanced glucose uptake activity in the myoblast and also has an indirect effect through stimulation of insulin secretion in the pancreatic β cell." (PMID 26675132, 2015). "This is characterized by impaired insulin-stimulated glucose uptake by peripheral tissues and subsequent hyperglycemia, in addition to abnormalities in hepatic insulin signaling leading to elevated blood lipids and gluconeogenesis and lower glycogen and HDL levels." (PMID 26497894, 2015). "When there is a severe degree of hyperglycemia, in the absence of insulin, this causes a rise in the plasma osmolarity thus forcing water to shift from the intracellular compartment to the extracellular compartment." (PMID 26553121, 2015). "This incomplete control of hyperglycemia may further explain weaker promotion of berberine on osseointegration compared with insulin." (PMID 26783411, 2015). "In addition, several studies showed that transplantation of human skeletal myoblasts (hSkMs) into hindlimb muscles improves insulin sensitivity and attenuates hyperglycaemia in KK mice, which is a model of T2DM." (PMID 26075247, 2015). "Receptor trafficking can occur relatively rapidly in the dorsal vagal complex, and occurs in this model of type 1 diabetes, where TRPV1 receptors are internalized after several days of hyperglycemia/hypoinsulemia and can be trafficked to the membrane of synaptic terminals by exposure to insulin." (PMID 25799386, 2015). "This device could also be used in regard of hyperglycemia risk, for VLBW newborns, in hyperinsulinism or in neonates with a risk of glucidic intolerance, to help to manage insulin infusion." (PMID 25590334, 2015).
Hyperglycemia (continued). "Hyperglycemia, moreover, can be reflecting the shortage of insulin." (PMID 26494998, 2015). "Individuals with post-prandial hyperglycaemia exhibit decreased insulin secretion after food consumption and less inhibition on the release of glucagon, leading to aberrant hepatic and renal glucose production, reduced glucose uptake by cells and consequently elevated blood glucose levels." (PMID 26308010, 2015). "Thus, insulin likely acts as an antioxidant under conditions of hyperglycaemia, leading to protection of the fetoplacental endothelium in diseases associated with endothelial dysfunction such as GDM." (PMID 25875935, 2015). "Hyperglycemia and the diminished effects, or complete lack, of insulin modify metabolic processes, thus contribute to the accelerated production of oxidative stress and irreversible metabolic by-products that pathologically alter cellular structure and function in many organs." (PMID 26197936, 2015). "In conclusion, we developed the first Brazilian application software that can use human insulin (NPH and regular) or insulin analogues (glargine, detemir, lispro, aspart and glulisine) as options for inpatient hyperglycemia management, and therefore it can be a useful tool for all public hospitals." (PMID 26697118, 2015). "Hyperglycaemia results from inhibition of insulin secretion." (PMID 27047082, 2015). "The uncontrolled hyperglycemia resulted in increased insulin requirement, up to 4 times." (PMID 26273667, 2015). "Increased mitochondrial ATP production in response to hyperglycemia closes the ATP-sensitive potassium channel, leading to membrane depolarization, opening of voltage-sensitive calcium channel, calcium ion influx, and insulin granule exocytosis." (PMID 26613076, 2015). "Similarly, in islets of diabetic KKAy mice, the number of c-Jun-positive cells was increased with marked hyperglycemia, and both MafA and insulin protein levels were decreased in those cells." (PMID 25794287, 2015). "Moreover, patients should be given instructions on how to initiate subcutaneous insulin supplementation in the event of hyperglycemia." (PMID 26078998, 2015). "On the other hand, defects in the liver insulin signaling pathway might promote inadequate suppression of gluconeogenesis, leading to hyperglycemia during fasting and after meals." (PMID 26288661, 2015). "In insulin dependent (Type 2) DM, defective insulin secretion can result from impaired β-cell function, oxidative stress, the absence of inhibitory feedback through plasma glucagon levels, chronic exposure to free fatty acids, lipotoxicity, and hyperglycemia." (PMID 26064426, 2015). "In IR individuals with T2DM the lack of compensatory insulin release causes a vicious cycle with worsening fatty acid-induced hyperglycemia." (PMID 26106623, 2015). "Control of hyperglycemia with insulin prevented the development of proteinuria." (PMID 26169541, 2015). "Furthermore, investigations in animal models have shown that infusion of insulin and proinsulin, as well as acute hyperglycemia and hyperinsulinemia, increased expression of PAI-1." (PMID 26089884, 2015). "UD rats showed sustained hyperglycemia, high glycosylated hemoglobin, and low plasma insulin." (PMID 25789328, 2015). "This is consistent with our finding in the present study in which PKCα was down-regulated in pancreatic islets of GK compared with Wistar rats, with intermediate expression in insulin-treated GK rats, suggesting a contribution of hyperglycaemia to the reduced levels in GK rat islets." (PMID 26398746, 2015). "Chronic hyperglycemia increases apoptosis and reduces glucose-stimulated insulin secretion." (PMID 26167511, 2015). "Hence, the precise mechanism by which CGE ameliorated hyperglycaemia and hypertriglyceridemia and restored the whole body insulin sensitivity in T2DM requires further investigation." (PMID 25883984, 2015).